LRRN1 (leucine rich repeat neuronal 1)
Synonyms: NLRR-1; FIGLER3; NLRR1
Tractability: Antibody: UniProt predicts a signal peptide or a membrane-spanning region; its Gene Ontology location is reachable by antibodies, with medium confidence. PROTAC: ubiquitination databases record sites on it; its protein half-life has been measured.
Gene: Protein-coding gene on chromosome 3 (3,799,378 to 3,849,834, forward strand). Ensembl gene ENSG00000175928.
Subcellular location: Membrane
Subcellular location (Human Protein Atlas): Endoplasmic reticulum; Basal body; Centriolar satellite; Golgi apparatus; Vesicles
Gene Ontology:
Molecular function: protein binding; signaling receptor activity
Cellular component: plasma membrane; membrane
Genetic constraint (gnomAD): Loss-of-function variants: 13 observed, 41.18 expected, observed/expected ratio (o/e) 0.32, 90% interval 0.2 to 0.5. The upper end of that interval is the gene's LOEUF score, 0.5, which puts it in group 2 of 6, group 1 being the genes least tolerant of losing a copy. Missense variants: 693 observed, 812.71 expected, observed/expected ratio (o/e) 0.85, 90% interval 0.8 to 0.91. Synonymous variants: 308 observed, 309.82 expected, observed/expected ratio (o/e) 0.99, 90% interval 0.9 to 1.09.
Homologues: Orthologues: chimpanzee LRRN1 (99% identical), macaque LRRN1 (99% identical), dog LRRN1 (97% identical), guinea pig LRRN1 (96% identical), pig LRRN1 (96% identical), mouse Lrrn1 (96% identical), rat Lrrn1 (96% identical), rabbit LRRN1 (94% identical), tropical clawed frog lrrn1l (81% identical), zebrafish lrrn1 (80% identical). Paralogues in human: LRRN3 (53% identical), LRRN2 (47% identical), LINGO2 (23% identical), SLIT1 (21% identical), LINGO1 (21% identical), SLIT2 (21% identical), SLIT3 (21% identical), LRFN5 (20% identical), LRFN2 (20% identical), LRFN4 (19% identical), LRRC70 (19% identical), LRFN1 (19% identical), and 13 more.
Diseases named in the same sentence as LRRN1 in open-access papers:
LRRN1 is named in the same sentence as 23 diseases in open-access papers, as found by Europe PMC text mining. Sharing a sentence is not in itself a finding about the gene and the disease. The quoted sentences say what the papers report.
neuroblastoma (5 papers, 2019 to 2025). Neuroblastoma (NB) is the most common solid, extracranial childhood tumor. "LRRN1 is involved in the regulation of proliferation and can protect cells from FBS deprivation-induced apoptosis in neuroblastoma cells." (PMID 35440048, 2022). "In embryonic SCs, LRRN1, alias NLRR1, was one of four genes markedly higher expressed than in fibroblasts and in a xenograft mouse model, LRRN1 expression in neuroblastoma cells resulted in enhanced tumor growth." (PMID 31083655, 2019).
breast carcinoma (4 papers, 2010 to 2025). "During our analysis, we found that LRRN1 expression demonstrated a significant association with key pathological characteristics of breast cancer and exhibited potential clinical relevance throughout the analysis." (PMID 41458604, 2025). "Our findings demonstrate significant associations between LRRN1 expression and the efficacy of several TKIs that are potentially used in breast cancer therapy such as Lapatinib, Bortezomib, Axitinib, and Afatinib." (PMID 41458604, 2025). "However, the specific mechanisms underlying LRRN1’s actions, as well as its potential clinical applications, still require further exploration to fully translate these findings into clinical practice for advanced breast cancer treatment." (PMID 41458604, 2025). "LRRN1 was found to be significantly downregulated in advanced breast cancer tissues compared to normal tissues (p < 0.001)." (PMID 41458604, 2025). "This study aimed to address this research gap by focusing on the leucine-rich repeat neuronal (LRRN) family, with the goal of clarifying their expression, clinical value, and prognostic significance in breast cancer—particularly LRRN1 in advanced cases." (PMID 41458604, 2025). "In an effort to identify clinically relevant factors within breast cancer, we systematically interrogated multiple breast cancer databases, highlighting LRRN1 as a particularly significant biomarker." (PMID 41458604, 2025). "Nevertheless, the mechanisms and functions of LRRN proteins in breast cancer remain largely unexplored, our study fills this gap by focusing on LRRN1, a previously understudied LRRN subfamily member, and revealing its tumor-suppressive role." (PMID 41458604, 2025). "It further analyzed the clinical value of these LRRN family members and specifically identified the prognostic significance of LRRN1 in advanced breast cancer cases." (PMID 41458604, 2025). "Building upon our previous findings that identified LRRN1 as a clinically significant factor in breast cancer, we proceeded to investigate its functional role in malignant progression." (PMID 41458604, 2025). "Collectively, our findings suggest that LRRN1 inhibits breast cancer metastasis by regulating the expression of key metastasis-associated proteins." (PMID 41458604, 2025). "To explore the potential therapeutic value of LRRN1 in breast cancer, we analyzed drug sensitivity data from the GSDC database." (PMID 41458604, 2025). "To further evaluate the clinical therapeutic value of LRRN1 in breast cancer, we performed GSEA on the TCGA-BRCA cohort, stratified according to LRRN1 expression levels." (PMID 41458604, 2025). "The results indicated that Wnt5A exhibited a significant positive correlation with LRRN1 in breast cancer." (PMID 41458604, 2025). "Overall, LRRN1 emerges as a promising prognostic indicator and functional mediator in advanced breast cancer." (PMID 41458604, 2025). "Elevated LRRN1 expression demonstrated a significant correlation with adverse prognosis in breast cancer patients." (PMID 41458604, 2025). "Western blot validation confirmed that overexpression of LRRN1 increased Wnt5A protein levels in two breast cancer cells." (PMID 41458604, 2025). "our analysis and experimental findings suggest that LRRN1 suppresses breast cancer metastasis and exhibits promising prognostic value for metastatic breast cancer." (PMID 41458604, 2025). "Moreover, high LRRN1 expression correlated with better disease-free survival (DFS) in advanced breast cancer patients (HR=0.755, 95% CI: 0.617–0.923, p < 0.01)." (PMID 41458604, 2025). "Collectively, these findings support our hypothesis that LRRN1 inhibits breast cancer metastasis through modulation of the Wnt signaling pathway." (PMID 41458604, 2025). "By modulating LRRN1 expression or activity, it may be possible to sensitize breast cancer cells to TKI treatment, thereby improving therapeutic outcomes." (PMID 41458604, 2025).
breast carcinoma (continued). "This suggests that LRRN1 may modulate the γδ T cells’ activity in the breast cancer immune TME, potentially influencing antitumor immunity." (PMID 41458604, 2025). "Further investigation into the mechanisms and functional confirmation of LRRN1 in breast cancer, particularly in TNBC, may provide valuable insights for developing novel immunotherapeutic strategies targeting this disease." (PMID 41458604, 2025). "The correlation of LRRN1 expression and clinical pathological parameters in breast cancer patients." (PMID 41458604, 2025). "Collectively, our findings suggest that LRRN1 activators may represent a promising therapeutic strategy for the treatment of breast cancer." (PMID 41458604, 2025). "We assessed then the correlation between these genes and LRRN1 in breast cancer." (PMID 41458604, 2025). "However, transwell migration and invasion assays showed that LRRN1 overexpression significantly suppressed the migratory and invasive capacities of breast cancer cells." (PMID 41458604, 2025). "We overexpressed LRRN1 in breast cancer cells and evaluated its biological impact." (PMID 41458604, 2025). "However, a critical gap remains: Although studies investigating LRRN1 in breast cancer remain limited, exploring the functions of the LRRN protein family may facilitate the identification of novel therapeutic targets." (PMID 41458604, 2025). "Additionally, LRRN1 could potentially modulate the M1/M2 balance macrophages in breast cancer TME, thereby influencing antitumor immune responses." (PMID 41458604, 2025). "Surprisingly, the proliferation assays demonstrated that LRRN1 overexpression had no significant impact on breast cancer cell proliferation." (PMID 41458604, 2025). "LRRN1 overexpression consistently downregulated the protein expression of focal adhesion kinase (FAK), matrix metalloproteinase-2 (MMP2), and matrix metalloproteinase-9 (MMP9) in both breast cancer cellines." (PMID 41458604, 2025). "Notably, our analysis revealed significant downregulation of LRRN1, LRRN3, and LRRN4CL in breast cancer tissues." (PMID 41458604, 2025). "The observed differential expression patterns, particularly the consistent downregulation of LRRN1, LRRN3, and LRRN4CL coupled with LRRN2 upregulation, prompted us to focus our subsequent investigations on elucidating the specific mechanisms of these proteins in breast cancer metastasis." (PMID 41458604, 2025).
gastric cancer (3 papers, 2021 to 2025). A primary or metastatic malignant neoplasm involving the stomach. "For example, the expression of LRRN1 was upregulated in gastric cancer tissues and LRRN1 was related to the poor prognosis." (PMID 34919118, 2021). "Meanwhile, elevated LRRN1 expression could inhibit apoptosis in gastric cancer by downregulating the Fas/FasL signaling cascade." (PMID 41458604, 2025). "Meanwhile, LRRN1 suppresses the apoptosis of gastric cancer cells." (PMID 35440048, 2022). "In addition, LRRN1 has been reported to correlate with other genes, including SNCG, GAMT, and PDE1B, collectively exhibiting prognostic value in gastric cancer." (PMID 41458604, 2025).
Obesity (2 papers, 2021 to 2023). Accumulation of substantial excess body fat. "The RNA seq gene signature include Neurensin 1 (Nrsn1) and Leucine rich repeat neuronal 1 (Lrrn1) in which polymorphisms in these gene have been linked to changes in food intake and obesity." (PMID 37604246, 2023).
brain cancer (1 paper, 2021). A primary or metastatic malignant neoplasm affecting the brain. "Higher levels of LRRN1 expression promote tumor cell proliferation, inhibiting cell apoptosis, and play an important role in preserving pluripotency-related proteins through AKT phosphorylation, leading to a poor clinical outcome in gastric and brain cancer." (PMID 34311724, 2021).
lymph node metastasis (1 paper, 2025). "Quantitative assessment demonstrated statistically significant inverse correlations between LRRN1 expression levels and advanced AJCC stage, larger tumor size, and lymph node metastasis." (PMID 41458604, 2025).
tumor (10 papers, 2013 to 2025). "Multivariate analysis revealed statistically significant correlations between LRRN1 expression levels and key clinicopathological parameters, including tumor size (p = 0.003), lymph node metastasis (p = 0.049), distant metastasis (p = 0.034), and advanced pathological stage (p = 0.002)." (PMID 41458604, 2025). "Additionally, LRRN1 may activate γδ T cells and resting dendritic cells, regulate the M1/M2 macrophage balance in the tumor microenvironment (p<0.001), and mediate the efficacy of certain tyrosine kinase inhibitors (TKIs) (p<0.001)." (PMID 41458604, 2025). "Multiple tumor suppressors were expressed at lower levels in EBVaGCs including five (TFF2, RBP4, HOXA9, LRRN1, and RAP1GAP) that are known to be hypermethylated in cancers." (PMID 23671415, 2013). "In contrast to LRRN1’s expression profile, LRRN2 exhibited significant upregulation in cancer tissues, though its associations with AJCC stage and tumor size showed only marginal trends without statistical significance." (PMID 41458604, 2025). "These genes include tumor suppressors or candidates (VHL, CTDSPL, LRRC3B, ALDH1L1, and EPHB1) and genes that were not previously considered as cancer-associated (e.g., LRRN1, GORASP1, FGD5, and PLCL2)." (PMID 24977159, 2014).
cancer (7 papers, 2013 to 2025). A tumor composed of atypical neoplastic, often pleomorphic cells that invade other tissues. "Among members of LRRN protein families, accumulating evidence has demonstrated that LRRN1 possesses both diagnostic and prognostic potential across various cancer types." (PMID 41458604, 2025). "Functional assays (assessing proliferative, migratory, and invasive capabilities of cancer cells) were conducted to evaluate LRRN1’s biological effects." (PMID 41458604, 2025). "Our analysis revealed LRRN1’s expression was lowly expressed in cancer tissues." (PMID 41458604, 2025). "Genes that are associated with increased proliferation and invasion in several cancer types, such as DPT, ANPEP, and LRRN1, were among the most concordant DEG in this signature." (PMID 34311724, 2021). "Functional assays revealed that LRRN1 suppresses cancer cell metastasis (without affecting cancer cell proliferation) (p<0.01)." (PMID 41458604, 2025). "But there are also a number of genes which have not been previously reported as involved in cancer development, such as LRRN1, GORASP1, FGD5, and PLCL2." (PMID 24977159, 2014).
LRRN1 also shares sentences with these, for which no sentence is quoted: dementia (2 papers); adenocarcinoma (1); Autoimmunity (1); colorectal cancer (1); head and neck squamous cell carcinoma (1); Insulin resistance (1); invasive breast carcinoma (1); keratoconus (1); lung carcinoma (1); meningioma (1); prostate carcinoma (1); squamous cell carcinoma (1); Stroke (1); triple-negative breast carcinoma (1); type 1 diabetes (1).